RNU6-1254P (RNA, U6 small nuclear 1254, pseudogene)
Gene: Small nuclear RNA gene on chromosome 7 (66,891,188 to 66,891,291, forward strand). Ensembl gene ENSG00000212568.
Homologues: Orthologues: chimpanzee U6 (99% identical), macaque U6 (89% identical), pig U6 (83% identical), dog U6 (79% identical), pig U6 (78% identical). Paralogues in human: RNU6-912P (97% identical), RNU6-1052P (92% identical), RNU6-1319P (92% identical), RNU6-241P (92% identical), RNU6-747P (92% identical), RNU6-1076P (91% identical), RNU6-1100P (91% identical), RNU6-1118P (91% identical), RNU6-1217P (91% identical), RNU6-355P (91% identical), RNU6-447P (91% identical), RNU6-705P (91% identical), and 1289 more.